TNIP3 (TNFAIP3 interacting protein 3)
Description:
Binds to zinc finger protein TNFAIP3 and inhibits NF-kappa-B activation induced by tumor necrosis factor, Toll-like receptor 4 (TLR4), interleukin-1 and 12-O-tetradecanoylphorbol-13-acetate. Overexpression inhibits NF-kappa-B-dependent gene expression in response to lipopolysaccharide at a level downstream of TRAF6 and upstream of IKBKB. NF-kappa-B inhibition is independent of TNFAIP3 binding.
Synonyms: ABIN-3; LIND; FLJ21162
Tractability: Antibody: the Human Protein Atlas places it where antibodies can reach.
Gene: Protein-coding gene on chromosome 4 (121,131,408 to 121,227,615, reverse strand). Ensembl gene ENSG00000050730.
Subcellular location (Human Protein Atlas): Cytosol; Nucleoplasm; Nuclear bodies; Plasma membrane
Pathways (Reactome):
Metabolism of proteins: Ovarian tumor domain proteases
Gene Ontology:
Molecular function: polyubiquitin modification-dependent protein binding; protein binding
Biological process: cellular response to lipopolysaccharide; MyD88-independent toll-like receptor signaling pathway; negative regulation of canonical NF-kappaB signal transduction; toll-like receptor 4 signaling pathway; regulation of transcription by RNA polymerase II; regulation of canonical NF-kappaB signal transduction
Cellular component: cytosol; cytoplasm
Genetic constraint (gnomAD): Loss-of-function variants: 30 observed, 40.66 expected, observed/expected ratio (o/e) 0.74, 90% interval 0.55 to 1. The upper end of that interval is the gene's LOEUF score, 1, which puts it in group 4 of 6, group 1 being the genes least tolerant of losing a copy. Missense variants: 311 observed, 346.19 expected, observed/expected ratio (o/e) 0.9, 90% interval 0.82 to 0.99. Synonymous variants: 118 observed, 124.43 expected, observed/expected ratio (o/e) 0.95, 90% interval 0.82 to 1.11.
Homologues: Orthologues: macaque TNIP3 (92% identical), chimpanzee TNIP3 (90% identical), dog TNIP3 (77% identical), guinea pig TNIP3 (72% identical), rabbit TNIP3 (71% identical), pig TNIP3 (67% identical), rat Tnip3 (40% identical), mouse Tnip3 (39% identical), tropical clawed frog tnip3 (33% identical). Paralogues in human: TNIP1 (37% identical), TNIP2 (14% identical).
Diseases named in the same sentence as TNIP3 in open-access papers:
TNIP3 is named in the same sentence as 21 diseases in open-access papers, as found by Europe PMC text mining. Sharing a sentence is not in itself a finding about the gene and the disease. The quoted sentences say what the papers report.
autoimmune disease (2 papers, 2023). A disorder resulting from loss of function or tissue destruction of an organ or multiple organs, arising from humoral or cellular immune responses of the individual to their own tissue constituents. "A number of autoimmune diseases have been associated with the TNIP3 protein and related mutations." (PMID 37345090, 2023). "Although CD is a heterogeneous autoimmune disease, the expression levels of five key genes (TNF, BIRC3, ANXA1, TNIP3, and FKBP11) were significantly higher in most CD tissues than that in normal tissues." (PMID 37047025, 2023).
cardiac hypertrophy (2 papers, 2024). "To clarify the role of TNIP3 in pathological cardiac hypertrophy, we constructed global Tnip3 knockout (KO) mice and the deficiency of TNIP3 was identified by western blot analysis." (PMID 38926347, 2024). "Taken together, these results indicated that TNIP3 deficiency exacerbated cardiac hypertrophy induced by pressure overload." (PMID 38926347, 2024). "Thus, TNIP3 deficiency promoted cardiac dysfunction in pathological cardiac hypertrophy after pressure overload." (PMID 38926347, 2024). "In Tnip3-deficient mice, cardiac hypertrophy was aggravated after TAC surgery." (PMID 38926347, 2024). "To further explore the influence of TNIP3 in cardiomyocytes on cardiac hypertrophy, we generated cardiomyocyte-specific Tnip3 transgenic (TG) mice by α-MHC promoter." (PMID 38926347, 2024). "Here, we identified the first evidence that TNFAIP3 interacting protein 3 (TNIP3) was a negative regulator of pathological cardiac hypertrophy." (PMID 38926347, 2024). "Mice with cardiac-specific overexpression of TNIP3 also suppressed mRNA and protein level of cardiac hypertrophy and fibrosis marker." (PMID 38926347, 2024). "Our data also showed that TNIP3 increased protein level of STAT1 in cardiac hypertrophy and even in hypertrophic cardiomyocytes under cycloheximide treatment." (PMID 38926347, 2024). "To illustrate the mechanism of how TNIP3 regulates pathological cardiac hypertrophy, we combined RNA-Seq and mass spectrometry data to analyze and identify STAT1 to serve as the potential target of TNIP3." (PMID 38926347, 2024). "In summary, this study demonstrates for the first time that TNIP3 plays an important role in protecting against pathological cardiac hypertrophy." (PMID 38926347, 2024). "In present study, our findings revealed a significant upregulation of TNIP3 expression in cardiac hypertrophy." (PMID 38926347, 2024). "In this study, we found that the expression of TNIP3 was significantly increased in cardiac hypertrophy model in vivo and in vitro." (PMID 38926347, 2024). "Remarkably, preservation effect of TNIP3 on cardiac hypertrophy was blocked by STAT1 inhibitor Fludaradbine or STAT1 knockdown." (PMID 38926347, 2024). "Conversely, cardiac-specific Tnip3 transgenic mitigated the progression of pathological cardiac hypertrophy in mice." (PMID 38926347, 2024). "To further reveal the mechanism of TNIP3 on cardiac hypertrophy, we combined analysis of RNA-sequencing in heart tissues and cardiomyocytes to search for potential targets of TNIP3 based on Kyoto Encyclopedia of Genes and Genomes (KEGG) database." (PMID 38926347, 2024). "Recent studies have implicated tumour necrosis factor alpha-induced protein 3-interacting protein 3 (TNIP3) in pathological cardiac hypertrophy." (PMID 39800969, 2024). "Mechanistically, RNA-sequencing and interactome analysis were combined to identify the signal transducer and activator of transcription 1 (STAT1) as a potential target to clarify the molecular mechanism of TNIP3 in pathological cardiac hypertrophy." (PMID 38926347, 2024). "This study further investigated the function of TNIP3 in pathological cardiac hypertrophy." (PMID 38926347, 2024). "Collectively, these data indicated that the reduction of STAT1 could abolish the protective effect of TNIP3 against cardiac hypertrophy." (PMID 38926347, 2024). "Considering the promotive effect of TNIP3 on total STAT1 protein during cardiac hypertrophy, we further investigated whether TNIP3 could affect the degradation of STAT1." (PMID 38926347, 2024). "Cardiac remodeling was essential in pathological cardiac hypertrophy, therefore we further explored whether TNIP3 could regulate this process in hypertrophic mice hearts." (PMID 38926347, 2024). "To investigate whether TNIP3 participated in regulation of pathological cardiac hypertrophy, we successfully conducted the model of cardiac hypertrophy in mice subjected to TAC surgery." (PMID 38926347, 2024).
cardiac hypertrophy (continued). "Overall, these results showed that TNIP3 was upregulated in vivo and in vitro in response to pressure overload, indicating that TNIP3 might be involved in the development of pathological cardiac hypertrophy." (PMID 38926347, 2024). "Therefore, TNIP3 overexpression relieved TAC induced pathological cardiac hypertrophy." (PMID 38926347, 2024). "Our study found that TNIP3 serves as a novel suppressor of pathological cardiac hypertrophy by promoting STAT1 stability, which suggests that TNIP3 could be a promising therapeutic target of pathological cardiac hypertrophy and heart failure." (PMID 38926347, 2024). "Notably, the absence of TNIP3 led to enhanced cardiomyocyte hypertrophy and cardiac interstitial fibrosis in mouse model of cardiac hypertrophy induced by transverse aortic constriction (TAC)." (PMID 38926347, 2024). "However, the role of TNIP3 in cardiovascular diseases, especially cardiac hypertrophy, has not been reported, highlighting a current gap in our understanding of this area." (PMID 38926347, 2024).
heart failure (2 papers, 2024). Inability of the heart to pump blood at an adequate rate to meet tissue metabolic requirements. "TNIP3 represents a novel therapeutic target for the treatment of heart failure-related VAs." (PMID 39800969, 2024).
nonalcoholic steatohepatitis (2 papers, 2024 to 2025). "Focusing on research in cardiovascular metabolic diseases for several years, our previous studies have demonstrated that TNIP3 acts as a novel endogenous suppressor of nonalcoholic steatohepatitis by interrupting TAK1 activation." (PMID 38926347, 2024). "Our previous studies demonstrated that TNIP3 acts as a novel negative regulator of nonalcoholic steatohepatitis and hepatic ischemia/reperfusion injury." (PMID 38926347, 2024).
breast carcinoma (1 paper, 2020). "rs4455437 is a SNP located ~30 kb downstream of the TNIP3 gene and was recently associated with breast cancer in African American women." (PMID 32850701, 2020).
colon cancer (1 paper, 2023). "In the dataset TCGA, high expression of TNF and TNIP3 was strongly associated with a better prognosis in colon cancer." (PMID 37047025, 2023). "Therefore, in combination with multi-dataset analysis, TNIP3 may be an independent factor in assessing colon cancer prognosis." (PMID 37047025, 2023).
Hyperglycemia (1 paper, 2025). An increased concentration of glucose in the blood. "A20 and TNIP-3, two well-established negative regulators of the NF-κB pathway, were significantly upregulated in ECs exposed to hyperglycemia compared with the normoglycemic control (p < 0.05 for both)." (PMID 41369397, 2025). "Our data reveal that ECs exposed to hypoxia, alone or combined with hyperglycemia, develop a non-canonical form of senescence characterized by the absence of classical SASP factors and the induction of A20 and TNIP-3." (PMID 41369397, 2025).
Myocardial fibrosis (1 paper, 2024). "Additionally, overexpression of TNIP3 significantly improved cardiac function, inhibited myocardial fibrosis, and suppressed proinflammatory response by promoting M1 to M2 macrophage polarization." (PMID 39800969, 2024).
psoriasis (1 paper, 2023). An autoimmune condition characterized by red, well-delineated plaques with silvery scales that are usually on the extensor surfaces and scalp. "It induces the expression of other psoriasis signature genes, such as IL36G, S100A15, DEFB4A, S100A9, CXCL8, TNIP3 (coding TNF-α-induced-protein 3 or TNFAIP3), and LCN2 (by synergy of IL-17C with TNF-α) in keratinocytes." (PMID 36928592, 2023).
infection (5 papers, 2019 to 2025). The state of being infected such as from the introduction of a foreign agent such as serum, vaccine, antigenic substance or organism. "TNFAIP3 interacting protein 3 (TNIP3), also known as ABIN3, was initially identified in human monocyte-like macrophages during infection with Listeria monocytogenes." (PMID 38926347, 2024). "TNIP3 was initially identified in human monocyte-like macrophages during infection with Listeria monocytogenes." (PMID 39800969, 2024). "Strikingly, in our study the TNFAIP3 interacting protein (TNIP3) was also differentially regulated as well as the adjacent lncRNA further suggesting that MAP-induced lncRNAs influence macrophage response towards infection." (PMID 30733564, 2019). "The data showed that the overexpression of miR-144-3p failed to downregulate and significantly upregulated the mRNA expression of TNIP3 and SARM1 in human MDMs before and after infection with Mabc or Mmass." (PMID 33473145, 2021).
cancer (3 papers, 2015 to 2024). A tumor composed of atypical neoplastic, often pleomorphic cells that invade other tissues. "We do not find any evidence of a differential expression of TNIP3 or of other cancer-related genes in the presence of rs4455437." (PMID 32850701, 2020).
inflammation (2 papers, 2022 to 2024). Aberrant reaction of the microcirculation characterized by movement of fluid and leukocytes from the blood into extravascular tissues. "And PI3K/Akt signalling inhibition offset the protective effect of TNIP3 overexpression on ISO-induced cardiac inflammation and VAs." (PMID 39800969, 2024).
tumor (1 paper, 2023). "Among them, ANXA1 and FKBP11 were highly expressed in tumor tissues compared to normal tissues, whereas BIRC3 and TNIP3 were lowly expressed in tumor tissues." (PMID 37047025, 2023).
TNIP3 also shares sentences with these, for which no sentence is quoted: inflammatory bowel disease (2 papers); Autoimmunity (1); COVID-19 (1); melanoma (1); metastatic tumors (1); Sepsis (1); systemic lupus erythematosus (1); tobacco use disorder (1).